GABRB3 (gamma-aminobutyric acid type A receptor subunit beta3)
Diseases named in the same sentence as GABRB3 in open-access papers (continued):
Sharing a sentence is not in itself a finding about the gene and the disease.
heroin dependence (1 paper, 2014). Physical and psychological dependence on the drug heroin. "A recent genetic study reported that a SNP (rs7165224) located at proximity of the GABRB3 gene was nominally associated with heroin addiction in a sample of African Americans, suggesting GABRB3 gene might be also associated with heroin dependence." (PMID 25025424, 2014). "Our data suggest that GABRB3 might be associated with heroin dependence, and increased expression of GABRB3 might contribute to the pathogenesis of heroin dependence." (PMID 25025424, 2014). "In conclusion, our data suggest that GABRB3 gene might be associated with heroin dependence, and increased GABRB3 gene expression might contribute to the pathogenesis of heroin dependence." (PMID 25025424, 2014). "Prompted by these findings, we were interested to know whether functional variants at the 5′ regulatory region of GABRB3 were associated with heroin dependence in our population." (PMID 25025424, 2014). "The study aimed to investigate whether SNPs at the 5′ regulatory region of GABRB3 were associated with heroin dependence in our population." (PMID 25025424, 2014). "As the C allele of haplotype C-A-G was the risk allele associated with heroin dependence in this study, our data suggested that increased GABRB3 gene expression might contribute to the pathogenesis of heroin dependence." (PMID 25025424, 2014). "Hence, if the association between GABRB3 gene and heroin dependence was further supported by other research groups, the GABRB3 gene could be considered as a shared susceptible gene among these neuropsychiatric disorders, not limited to heroin dependence." (PMID 25025424, 2014). "The association between GABRB3 and heroin dependence has not yet been well addressed in the literature." (PMID 25025424, 2014).
liver fibrosis (1 paper, 2024). "These genes, including Robo1, Gabrb3, Gpc6, Ephb2 and Dlg2, are usually not expressed in healthy liver, and were reported to be upregulated in metabolic dysfunction-associated steatohepatitis and liver fibrosis." (PMID 39456836, 2024).
medulloblastoma (1 paper, 2024). A malignant, invasive embryonal neoplasm arising from the cerebellum. "Here, we show the expression of genes encoding β subunits of the GABAA receptor, namely GABRB1, GABRB2, and GABRB3, across the four different molecular subgroups of medulloblastoma (MB), which is the most common malignant pediatric brain tumor." (PMID 39595908, 2024).
Obesity (1 paper, 2022). Accumulation of substantial excess body fat. "Two imprinted genes, namely GABRB3 and PRDM16, also showed differential methylation in both OBS and ALSPAC cohorts in male offspring from mothers with obesity." (PMID 35500004, 2022).
prostate carcinoma (1 paper, 2024). A carcinoma that arises from epithelial cells of the prostate gland. "To further elucidate the molecular mechanisms underlying the roles of GABRB3 in prostate cancer, we performed GSEA on prostate cancer tumors exhibiting high and low GABRB3 expression using the GO and Hallmark pathway databases." (PMID 38287309, 2024). "The upregulation of GABRB3 has been associated with the occurrence of brain metastases originating from diverse cancers, including prostate cancer." (PMID 38287309, 2024). "In this study, we performed a transcriptomic analysis to investigate the mechanisms associated with GABRB3 in human prostate cancer." (PMID 38287309, 2024). "A recent investigation revealed hypomethylation at the promoters of genes involved in neuroactive ligand-receptor interaction and cell adhesion molecules, such as GABRB3, in prostate cancer brain metastases." (PMID 38287309, 2024). "The results indicated a notably higher expression of GABRB3 in prostate cancer compared to normal prostate tissues (standardized mean difference = 0.58, 95% CI = 0.34–0.81, P < 0.001)." (PMID 38287309, 2024). "A comprehensive pooled analysis of 16 independent gene expression datasets revealed elevated expression of GABRB3 in prostate cancer tissues compared to that in normal tissues (P < 0.001)." (PMID 38287309, 2024). "This study revealed an intriguing link between GABRB3 and the survival of patients with prostate cancer undergoing ADT." (PMID 38287309, 2024). "Finally, while we present in silico functional evidence shedding light on the potential influence of GABRB3 on prostate cancer progression, further research is required to unravel the underlying mechanisms." (PMID 38287309, 2024). "Furthermore, we explored the biological functions of the implicated gene, gamma-aminobutyric acid type A receptor subunit beta 3 (GABRB3), to uncover plausible biological mechanisms affecting the progression of prostate cancer." (PMID 38287309, 2024). "Consequently, it is plausible that epigenetic dysregulation in primary prostate cancer leads to GABRB3 overexpression, subsequently activating the PI3K/AKT pathway and fostering resistance to ADT." (PMID 38287309, 2024). "However, further functional studies are warranted to validate our findings and elucidate the precise role of GABRB3 in the progression of prostate cancer." (PMID 38287309, 2024). "Furthermore, gene set enrichment analysis unveiled differential enrichment of pathways such as myogenesis, interferon γ and α responses, and the MYC proto-oncogene pathway in tumors with elevated GABRB3 expression, implying a role for GABRB3 in prostate cancer." (PMID 38287309, 2024).
prostate tumor (1 paper, 2024). "Additionally, a pooled analysis of 16 independent studies demonstrated that GABRB3 mRNA expression levels in prostate tumor tissue specimens were significantly higher than those in adjacent non-cancerous samples." (PMID 38287309, 2024).
retinal diseases (1 paper, 2023). "However, there is no research on the role of GABRB3 in retinal diseases." (PMID 37685269, 2023).
substance abuse (1 paper, 2014). The use of a drug for a reason other than which it was intended or in a manner or in quantities other than directed. "GABRB3 encoding the β3 subunit of GABAA receptor has been implicated in multiple neuropsychiatric disorders, including substance abuse." (PMID 25025424, 2014).
tauopathy (1 paper, 2018). Neurodegenerative disorders involving deposition of abnormal tau protein isoforms (tau proteins) in neurons and glial cells in the brain. "To begin to address this question, we examined temporal expression of Gabbr1, Gabrb2, Gabrb3, and Gabrg2 in a mouse model of tauopathy that overexpresses human MAPT p.P301L37." (PMID 30546007, 2018).
neurodevelopmental disorder (9 papers, 2014 to 2024). A behavioral and cognitive disorder with onset during the developmental period that involves impaired or aberrant development of intellectual, motor, or social functions.
tumor (7 papers, 2017 to 2026). "Functional experiments further showed that loss of GABRB3 or NRXN1 impaired tumor growth and brain colonization in xenograft models." (PMID 42034645, 2026). "Genes GABRA2 and GABRB3 had a Bonferroni-adjusted p value < 0.05 in these tumor samples." (PMID 38539663, 2024). "We went on to verify whether the GABRB3 gene, which showed significant associations with OS in GBM patients from the French cohort and also for TCGA-LGG patients when all tumor types were pooled together, would show influences on OS when lower grade tumors are analyzed separately." (PMID 38539663, 2024). "Interestingly, MCPyV-positive tumors were recently shown to display elevated expression of GABRB3 and K+ channel genes at the transcriptional level, which may play additional roles in the control of ionic balance during tumor growth." (PMID 29462791, 2018). "Our GSEA suggest that GABRB3 plays varying roles in myogenesis, interferon γ and α responses, and the MYC proto-oncogene pathway during tumor development." (PMID 38287309, 2024). "GABA receptor signaling pathway enrichment was defined by elevated expression of GABRB3 and potassium channel genes, KCNN1, KCNN2, and KCNQ3, and decreased expression of ADCY2, which have all been indicated as important in tumor growth (32, –, 34)." (PMID 28049147, 2017).
neurological disorders (5 papers, 2020 to 2025). "The regions of the 3 CNVs are located in chromosome Xp22.31, 15q11.2–13.1 and 17p11.2, and harbored genes associated with neurological diseases including GABRB3, UBE3A, MAGEL2, RAI1, ALDH3A2, ATPAF2 according to the database of Online Mendelian Inheritance in Man (OMIM)." (PMID 33753861, 2021). "GABRB3 is one of the genes classified under the GO term synaptic signaling, and has been extensively studied for its role in neurological disorders, including ASD." (PMID 38645217, 2024).
cancer (4 papers, 2019 to 2024). A tumor composed of atypical neoplastic, often pleomorphic cells that invade other tissues. "After multivariate Cox regression analysis and multiple testing correction, GABRB3 rs12591845 exhibited the most significant association with both overall and cancer-specific survivals (P < 0.003)." (PMID 38287309, 2024). "However, in the cancer cells, at the same genomic region at chromosome 15q12, the one large TAD is split into two smaller-size TADs and the GABRB3 gene is expressed." (PMID 31515496, 2019).
heart (1 paper, 2022). "Collectively, these results highlight the far-reaching consequences of vascular Gabrb3 elimination on the heart and suggest that loss of a common molecule Gabrb3 from the vasculature of the brain and the heart, can contribute concurrently to brain–heart dysfunction." (PMID 35318369, 2022).
infection (1 paper, 2022). The state of being infected such as from the introduction of a foreign agent such as serum, vaccine, antigenic substance or organism. "Furthermore, we found that GABRD, GABRB3, GABRE, and GABRQ, which play important roles in neuron cell growth and migration, are significantly downregulated after infection." (PMID 36147849, 2022).
GABRB3 also shares sentences with these, for which no sentence is quoted: Seizure (3 papers); Doose syndrome (2); Dyskinesia (2); Dystonia (2); febrile seizures (2); fibromyalgia (2); infantile epileptic encephalopathy (2); insomnia (2); microcephaly (2); movement disorder (2); panic disorder (2); psychiatric disorder (2); amyotrophic lateral sclerosis (1); astrocytoma (1); atherosclerosis (1); Athetosis (1); bipolar disorder (1); childhood-onset epileptic encephalopathy (1); Chorea (1); cocaine abuse (1); Dentatorubral pallidoluysian atrophy (1); dependence (1); developmental and epileptic encephalopathy (1); Distichiasis (1); dyspraxia (1); EARS disease (1); Encephalopathy (1); focal epilepsy (1); fragile X syndrome (1); gastric cancer (1).
A further 26 diseases each share a sentence with GABRB3 in 1 paper.